FOXE3 (forkhead box E3)
Description:
Transcription factor that controls lens epithelial cell growth through regulation of proliferation, apoptosis and cell cycle. During lens development, controls the ratio of the lens fiber cells to the cells of the anterior lens epithelium by regulating the rate of proliferation and differentiation (By similarity). Controls lens vesicle closure and subsequent separation of the lens vesicle from ectoderm (By similarity). Controls the expression of DNAJB1 in a pathway that is crucial for the development of the anterior segment of the eye.
Synonyms: FKHL12; FREAC8; AAT11; ASGD2; CATC3; CTRCT34
Tractability: No criterion of Open Targets' tractability assessment is met for any kind of drug.
Gene: Protein-coding gene on chromosome 1 (47,416,285 to 47,418,052, forward strand). Ensembl gene ENSG00000186790.
Subcellular location: Nucleus
Gene Ontology:
Molecular function: DNA binding; DNA-binding transcription factor activity; DNA-binding transcription factor activity, RNA polymerase II-specific; RNA polymerase II cis-regulatory region sequence-specific DNA binding; sequence-specific DNA binding
Biological process: eye development; lens development in camera-type eye; mRNA transcription by RNA polymerase II; negative regulation of apoptotic process; positive regulation of lens epithelial cell proliferation; regulation of cell cycle; transcription by RNA polymerase II; anatomical structure morphogenesis; cell differentiation; ciliary body morphogenesis; cornea development in camera-type eye; iris morphogenesis; negative regulation of lens fiber cell differentiation; regulation of transcription by RNA polymerase II; trabecular meshwork development; animal organ development; regulation of DNA-templated transcription; system development
Cellular component: nucleus; transcription regulator complex; chromatin
Genetic constraint (gnomAD): Loss-of-function variants: 1 observed, 0.36 expected, observed/expected ratio (o/e) 2.77. That is too few expected variants to judge how well the gene tolerates losing a copy. Missense variants: 466 observed, 317.49 expected, observed/expected ratio (o/e) 1.47, 90% interval 1.36 to 1.59. Synonymous variants: 245 observed, 157.02 expected, observed/expected ratio (o/e) 1.56, 90% interval 1.4 to 1.74.
Gene-disease validity (ClinGen):
ClinGen rates the evidence that FOXE3 causes each of these diseases.
anterior segment dysgenesis (semidominant): Definitive. A spectrum of developmental anomalies that affect the development of the anterior segment of the eyeball resulting from abnormalities of neural crest migration and differentiation during embryologic development (Axenfeld-Rieger syndrome, Peters anomaly, posterior keratoconus, and iridoschisis).
familial thoracic aortic aneurysm and aortic dissection (autosomal dominant): Moderate. A rare genetic vascular disease characterized by the familial occurrence of thoracic aortic aneurysm, dissection or dilatation affecting one or more aortic segments (aortic root, ascending aorta, arch or descending aorta) in the absence of any other associated disease.
Homologues: Orthologues: chimpanzee FOXE3 (99% identical), macaque FOXE3 (96% identical), pig FOXE3 (87% identical), dog FOXE3 (81% identical), mouse Foxe3 (75% identical), rat Foxe3 (74% identical). Paralogues in human: FOXE1 (46% identical), FOXD1 (34% identical), FOXD4 (34% identical), FOXC1 (33% identical), FOXD2 (33% identical), FOXC2 (32% identical), FOXD4L3 (32% identical), FOXD4L5 (32% identical), FOXD4L6 (32% identical), FOXD4L4 (32% identical), FOXD4L1 (32% identical), FOXL1 (31% identical), and 29 more.
Diseases named in the same sentence as FOXE3 in open-access papers:
FOXE3 is named in the same sentence as 33 diseases in open-access papers, as found by Europe PMC text mining. Sharing a sentence is not in itself a finding about the gene and the disease. The quoted sentences say what the papers report.
aphakia (14 papers, 2006 to 2025). "Transcription factor encoded by FOXE3 has a forked head DNA binding domain, and variants of FOXE3 are responsible for the dysgenesis of anterior segment tissues like lens and cornea resulting in microphthalmia, glaucoma, and aphakia." (PMID 32976546, 2020). "Similar phenotypes of congenital aphakia, microphthalmia, and anterior segment dysgenesis have been only reported for some FOXE3 and PAX6 mutations, two transcription factors involved in lens vesicle formation." (PMID 32791987, 2020). "Congenital aphakia is usually reported in association with other severe ocular conditions, such as the sclerocornea–microphthalmia–aphakia complex caused by FOXE3 mutations." (PMID 32791987, 2020). "In a previous report, we described a Mexican pedigree segregating an autosomal recessive ocular malformation characterized by bilateral sclerocornea, aphakia, and microphthalmia, caused by a FOXE3 p.Y98H mutation." (PMID 24019743, 2013). "Here, we report the characterization of a FOXE3 mutation identified in a consanguineous Pakistani family that results in primary congenital aphakia." (PMID 20361012, 2010). "Meanwhile, recessive mutations in FOXE3 have been identified in eight families with aphakia, microphthalmia, and sclerocornea as the principal phenotype." (PMID 20806047, 2010). "The aphakia phenotype suggested a mutation in FOXE3 close to the AR-locus 1p34.3-p32.2, and sequence analyses revealed the nonsense mutation c.720C>A, changing cysteine 240 to a stop codon." (PMID 20361012, 2010). "In humans, homozygous FOXE3 mutations have been associated both with recessive inherited congenital primary aphakia, and the dominant inheritance of ocular dysgenesis, cataracts and Peters’ anomaly." (PMID 20361012, 2010). "Interestingly, sclerocornea occurring with aphakia/abnormal lens phenotype is also associated with biallelic variants in FOXE3." (PMID 40301690, 2025). "FOXE3 variants are associated with a wide spectrum of anterior segment phenotypes and have been identified in patients with childhood glaucoma associated with Peters anomaly, congenital cataracts/aphakia and microphthalmia." (PMID 41011222, 2025). "The known pathogenic variants previously identified in FOXE3 are predominantly responsible for causing aphakia, sclerocornea, microphthalmia, anterior segment dysgenesis, and, rarely, increased intraocular pressure, bilateral congenital cataract, and vitreoretinal dysplasia." (PMID 37628625, 2023). "Furthermore, FOXE3 mutations have been found in patients with sclerocornea, microphthalmia, and bilateral aphakia." (PMID 20664696, 2010). "In the current study, we identified additional cases of sclerocornea, aphakia, and microphthalmia in that village and performed a molecular epidemiologic study to screen a large unselected sample of the residents to establish the carrier frequency of the FOXE3 p.Y98H mutation." (PMID 24019743, 2013). "Mutations in FOXE3 were reported to cause anterior segment ocular dysgenesis, including sclerocornea, microphthalmia, aphakia, and the absence of iris." (PMID 31781308, 2019). "The function of FOXE3 in lens development has been extensively studied in mice where homozygous null mutations result in congenital aphakia with the absence of lens development." (PMID 20361012, 2010). "Mutations in FOXE3 cause recessive sclerocornea in association with microphthalmia, bilateral aphakia, absence of the iris and retinal dysplasia (OMIM 610256)." (PMID 20664696, 2010). "We found that transcription factors implicated in vertebrate lens development (Prox1a, MafB, c-Maf, FoxE3) failed to initiate expression in the presumptive lens tissue of Pax6.1 mutant fish resulting in aphakia, a phenotype observed previously in Pax6 mutant mice." (PMID 39512904, 2024).
microphthalmia (14 papers, 2010 to 2025). Congenital or developmental anomaly in which the eyeballs are abnormally small. "Similarly, in a mixed cohort of Caucasians, Hispanics, African Americans, and Asians (n = 116), 15% of the bilateral microphthalmia patients were solved with FOXE3 variants." (PMID 37628625, 2023). "New phenotypic associations were found for FOXE3 (bilateral sensorineural hearing loss) and MAB21L2 (unilateral microphthalmia)." (PMID 36192130, 2023). "No pathogenic variants were identified in any other known microphthalmia-associated loci, specifically RAB3GAP2 and FOXE3, also located on chromosome 1." (PMID 33671840, 2021).
cataract (7 papers, 2010 to 2024). Partial or complete opacity of the crystalline lens of one or both eyes that decreases visual acuity and eventually results in blindness. "The mutation of Pitx3 and Foxe3 genes can cause the mesenchymal dysgenesis of anterior segment and cataracts in humans, and the knockdown of Pitx3 and Foxe3 in zebrafish via antisense morpholino results in the lens dysmorphogenesis." (PMID 34451814, 2021). "We chose the Foxe3 locus for gene targeting because its inactivation causes abnormal development of the eye and cataracts in mice." (PMID 29482575, 2018). "Several genes that cause congenital cataract in mice also contribute to human cataracts, including Cryg, Connexin, Foxe3 and Sox1." (PMID 28135291, 2017). "FoxE3 is associated with ocular dysgenesis and cataracts in humans (OMIM#601094)." (PMID 21896182, 2011).
glaucoma (6 papers, 2010 to 2025). Increased pressure in the eyeball due to obstruction of the outflow of aqueous humor. "From 21 glaucoma disease-associated genes with measurable expression, 2 were upregulated (MYOC and FOXE3) and five were downregulated (SH3PXD2B, NF1, SBF2, ADAMTS17, and FOXC1)." (PMID 35348588, 2022). "However, given FOXE3-associated glaucoma is a consequence of anterior segment dysgenesis, and MYOC contributes to glaucoma through accumulation of mutant MYOC protein aggregates, we suspect differential expression of these genes is unlikely to contribute to PEX glaucoma." (PMID 35348588, 2022). "Finally, the p.Arg90Leu dominant mutation affecting the DNA-binding domain of FOXE3 was associated with Peters’ anomaly and glaucoma, but not cataract." (PMID 20806047, 2010).
Anophthalmia (5 papers, 2011 to 2025). Absence of the globe or eyeball. "In comparison to this, affected individuals of family MA102 harboring the same FOXE3 variant showed complete anophthalmia." (PMID 37628625, 2023).
congenital cataracts (5 papers, 2010 to 2025). "Most genes are associated with isolated congenital cataracts while mutations in the transcription factor genes PAX6, FOXE3, EYA1, MAF, and PITX3 lead to congenital cataract with ASD." (PMID 24555714, 2014). "Additionally, cytoskeletal proteins and transcription factors, including Forkhead box protein E3 (FOXE3) and heat shock transcription factor 4 (HSF4), are associated with congenital cataracts." (PMID 40585754, 2025).
lens agenesis (3 papers, 2007 to 2018). "FOXE3 mutations, associated with lens agenesis, have been observed in a few microphthalmic patients." (PMID 18039390, 2007). "SOX2 and PAX6 mutations may cause lens induction failure, FOXE3 mutations are associated with lens agenesis, and OTX2, CHX10, and RAX may cause failure of retinal differentiation." (PMID 30153864, 2018).
Aortic dissection (2 papers, 2022). Aortic dissection refers to a tear in the intimal layer of the aorta causing a separation between the intima and the medial layers of the aorta. "Mutant forkhead box E3 (FOXE3) has been identified to predispose to aortic dissections." (PMID 36561772, 2022). "WES identified recurrent gain-of-function mutations in PRKG1 as causative for thoracic aortic aneurysms and acute aortic dissections, meanwhile MAT2A, LOX, and FOXE3 have been suggested as predisposing genes." (PMID 35892496, 2022).
aniridia (1 paper, 2010). Aniridia is a congenital ocular malformation characterized by the complete or partial absence of the iris. "A second sequence alteration in FOXE3 was identified in Patient 2 affected with aniridia, corneal limbal insufficiency, nystagmus, severe axile myopia, mild lens opacities, and development of a fibrous posterior capsular reaction after lens surgery." (PMID 20806047, 2010).
Loeys-Dietz syndrome (1 paper, 2024). Loeys-Dietz syndrome is a rare genetic connective tissue disorder characterized by a broad spectrum of craniofacial, vascular and skeletal manifestations with four genetic subtypes described forming a clinical continuum. "We did not identify any mutations of HTAD genes that cause Loeys-Dietz syndrome, which is associated with early onset TAD and BAV, and a total of three causal mutations in non-syndromic HTAD genes (a glycine substitution in FBN1 and loss of function mutations in SMAD4 and FOXE3)." (PMID 38370698, 2024).
cancer (2 papers, 2011 to 2023). A tumor composed of atypical neoplastic, often pleomorphic cells that invade other tissues. "Two of the genes (KIF17 and ATP8A2) showed no methylation in either cancer or matched tissues, and eight genes (EPHA4, OVOL1, UTF1, ADAM8, BOLL, FOXE3, GUCY1A2, and ADCY5) were equally methylated in the two groups." (PMID 21625442, 2011).
FOXE3 also shares sentences with these, for which no sentence is quoted: coloboma (2 papers); alopecia (1); autism (1); Bamforth-Lazarus syndrome (1); Blepharophimosis (1); Cirrhosis (1); developmental delay (1); Epicanthus inversus (1); hearing loss (1); intellectual disability with language impairment (1); language disorder (1); myopia (1); Nail dystrophy (1); Nystagmus (1); optic disc coloboma (1); sclerocornea (1); sensorineural hearing loss (1); T-cell immunodeficiency (1); thoracic aortic aneurysm (1); tumor (1); vitreoretinal dysplasia (1); WAGR syndrome (1).